CD99 (CD99 molecule (Xg blood group))
Diseases named in the same sentence as CD99 in open-access papers (continued):
Sharing a sentence is not in itself a finding about the gene and the disease.
neuroblastoma (14 papers, 2011 to 2025). Neuroblastoma (NB) is the most common solid, extracranial childhood tumor. "Ewing cells retained viability when incubated with an isotype control and CD99-negative Kelly neuroblastoma cells." (PMID 38534214, 2024). "When macrophages are co-incubated with a CD99-negative Kelly neuroblastoma cell line and incubated with both antibodies, there is little change in TNF-α decline." (PMID 38534214, 2024). "Other less specific markers such as CD56, CD9, CD57, CD81, CD99 also contributed to some differential diagnoses, e.g. the distinction between neuroblastoma and RMS (CD56,CD57,CD81) and between PNET and both RMS (CD9) and neuroblastoma (CD99, CD56, CD81 and CD57)." (PMID 23472067, 2013). "Neuroblastoma usually express neural antigens (NSE, neurofilament protein) and does not express CD99." (PMID 40950824, 2025). "None of the other markers tested (e.g. CD99, CD38, CD19, CD20, CyCD79a, CD34, numyogenin, nuMYOD1) was expressed by neuroblastoma cells." (PMID 23472067, 2013). "Immunohistochemistry is very useful to differentiate it from renal primitive neuroectodermal tumor/EWING tumor because neuroblastomas are consistently positive for NSE and chromogranin and mostly negative for CD99." (PMID 22312368, 2012). "The lesion revealed positive immunoexpression for vimentin and CD99 and negative immunostaining for desmin, CD45, cytokeratin, and neuroblastoma protein, suggesting, then, the diagnosis of PNET." (PMID 22242031, 2011). "Furthermore, the presence of Homer-Wright rosettes are typical for neuroblastomas, which are also positive for NSE, synaptophysine, and chromogranine A, but negative for CD99." (PMID 23537038, 2013).
breast carcinoma (13 papers, 2010 to 2024). "In human breast cancer, expression of the splice variant of CD99 increased the activity and expression of MMP-9 and contributed to the invasive phenotype by upregulating AP1-mediated gene expression through the AKT-dependent, ERK, and JNK signaling pathways." (PMID 29534016, 2018). "According to the literature, this is the first time that the peripheral blood levels of CD99 have been analysed for mammary tumours in any species." (PMID 37298173, 2023). "Such activity is also supported by the reduced expression of CD99 mRNA in breast cancer brain metastases compared to their matched primary tumours." (PMID 34374417, 2021). "In a xenograft model of breast cancer, tumour cell CD99 expression inhibited metastatic progression, and patient samples showed reduced expression of the CD99 gene in brain metastases compared to matched primary breast tumours." (PMID 34374417, 2021). "Our results identify a functional link between CD99, CDC42 and cytoskeletal dynamics in cancer cells and demonstrate that breast cancer CD99 negatively regulates CDC42 activity and TEM." (PMID 34374417, 2021). "Taken together, we propose that CD99 agonist ligands have potential as novel therapeutic drug candidates to suppress human breast carcinoma via inhibition of EGF-mediated EGFR signaling." (PMID 33050232, 2020). "Recently, another pathway has been described in a breast cancer model, where CD99-derived agonist ligands inhibit fibronectin-mediated β1 integrin activation, through the SHP2/ERK/PTPN12/FAK1 signaling pathway." (PMID 30845661, 2019). "We hypothesize that CD99‐mediated cell interactions may inhibit immune cells through some unknown mechanism, and therefore, it may be an effective target of breast cancer." (PMID 37021816, 2023). "Antagonism of EGFR-mediated signalling by breast cancer CD99 suggests that CD99 depletion might be associated with the increased growth of metastases in our model." (PMID 34374417, 2021). "In addition to this role in regulating growth factor responses, our data show that by negatively regulating CDC42 activity and actin reorganisation, tumour cell CD99 also modulates the TEM/metastasis of breast cancer." (PMID 34374417, 2021). "This suggested that breast cancer metastases in patients might demonstrate reduced CD99 expression compared to primary tumours." (PMID 34374417, 2021). "Moreover, CD99 agonist significantly suppressed tumor growth in a BALB/c mouse model injected with MDA-MB-231 human breast cancer cells." (PMID 33050232, 2020). "In addition, studies have shown that CD99 is lowly expressed as a tumor suppressor in a variety of malignancies, such as breast cancer, cervical cancer, and lung and gastric cancer." (PMID 31844676, 2019). "Canine mammary tumours induce variations in the peripheral concentrations of CD20, CD45RA, and CD99." (PMID 37298173, 2023). "In the breast cancer model, ∼30% of MDA-MB-231 cells depleted of CD99 were flattened onto the endothelial monolayer after 4 h, compared to ∼20% of the cells treated with control siRNA." (PMID 34374417, 2021). "We determined the expression of CD99 by the cell lines MCF7 and MDA-MB-231, which differ in their invasive potential; MCF7 is a non-invasive ER+ breast cancer cell line, whereas MDA-MB-231 is a highly invasive triple negative breast cancer cell line." (PMID 34374417, 2021). "The CD99 molecule has previously been linked to Rho GTPase activity, actin dynamics and growth factor signalling in breast cancer; EGFR stimulates RhoA and Rac1 activity and actin reorganization, and these pathways are antagonised by CD99-mediated signalling." (PMID 34374417, 2021). "Despite different levels of EGFR expression, these two breast carcinomas were similarly affected by EGFR ligands and CD99 agonists." (PMID 33050232, 2020). "In this study, we examined the molecular mechanism through which CD99 agonist ligand suppresses ligand-induced dimerization and internalization of EGFR in breast carcinoma cells." (PMID 33050232, 2020).
breast carcinoma (continued). "Assessment of cyclin D1, FOXP1, NRP1 and CD99 expression was repeated on a validation cohort of 82 BRCA1 and 65 sporadic basal-like breast cancers." (PMID 26152113, 2015). "It has been reported that CD99 expression is not prognostic in primary breast cancer; however, CD99-expressing tumours were present in low numbers in this study." (PMID 34374417, 2021). "Our study suggests that CD99-derived agonist ligands inhibit EGF-induced EGFR dimerization through impairing RhoA-Rac1 signaling-mediated reorganization of the actin cytoskeleton, thereby contributing to the suppression of breast cancer growth." (PMID 33050232, 2020). "Taken together, these results indicate that CD99-derived agonist ligand inhibits epidermal growth factor (EGF)-induced EGFR dimerization through impairment of cytoskeletal reorganization by PTPN12-dependent c-Src/FAK inactivation, thereby suppressing breast cancer growth." (PMID 33050232, 2020). "In breast carcinoma MCF-7 cells, CD99 may function as a negative regulator of FAK-mediated tumorigenesis and metastasis by recruiting the protein tyrosine phosphatase SHP2 which dephosphorylates FAK and blocks the positive pro-tumorigenic signaling of CD98/integrins/FAK/RhoA/ROCK." (PMID 29534016, 2018). "According to these results, both CD99 and CD45RA are indicators of mammary tumour presence, but without distinguishing between malignant and benign." (PMID 37298173, 2023). "CD99CRIII3 dose-dependently suppressed the growth of MDA-MB-231 human breast cancer cells implanted in nude mice, while it failed to suppress the growth of shPTPN12-MDA-MB-231 cells implanted in nude mice, suggesting that PTPN12 serves as a key executor of the CD99 signaling pathway." (PMID 33050232, 2020).
lymphoblastic lymphoma (13 papers, 2012 to 2026). A lymphoma composed of immature small to medium-sized precursor lymphoid cells (lymphoblasts). "The major diagnostic pitfalls are represented by distinction from lymphoblastic lymphomas (TdT+/CD34+/CD99+/CD45+/high Ki-67 index), and small round-cell tumours (CD99+/TdT-)." (PMID 27019694, 2016). "None of the cases with high-grade morphology expressed any primitive markers such as TdT, CD99, or CD34, thereby excluding lymphoblastic lymphoma." (PMID 39759724, 2024). "FLI-1 expression can lead to diagnostic confusion, especially in small blue round cell tumors, such as lymphoblastic lymphoma, plasmablastic lymphoma, and plasma cell myeloma, when distinguishing tumors positive for CD99 and CD56 without CD3, CD20, or CD45." (PMID 38280044, 2024). "The expression of FLI-1 can lead to serious diagnostic confusion, especially in small blue round cell tumors, when distinguishing tumors positive for CD99 and CD56 without CD3, CD20, or CD45, such as lymphoblastic lymphoma, PBL, and PCM." (PMID 38280044, 2024).
acute lymphoblastic leukemia (12 papers, 2016 to 2026). Leukemia with an acute onset, characterized by the presence of lymphoblasts in the bone marrow and the peripheral blood. "CD99 is a tumor-associated antigen that showed strong expression levels in T-acute lymphoblastic leukemia (T-ALL) but low expression levels in normal cells." (PMID 38804310, 2024). "This pathway is particularly interesting since the expression of CD99 in T cells is sought to detect minimal residual disease in acute lymphoblastic leukemia; and some clinical trials propose CD99 as a therapeutic target in AML." (PMID 41557613, 2026). "CD99 exhibited higher expression levels in T cell acute lymphoblastic leukemia (T-ALL) than normal T cells by about seven times." (PMID 39595598, 2024). "CD99 was also found to be highly expressed in acute lymphoblastic leukemia (ALL), acute myeloid leukemia (AML), myelodysplastic syndromes (MDS), and stem cells and anti-CD99 monoclonal antibodies show antileukemic activity in AML xenograft models." (PMID 31001265, 2019). "CD99 is highly expressed in T-lineage acute lymphoblastic leukemia (T-ALL), early B cell lymphoblastic lymphomas, immunophenotypic acute myeloid leukemia (AML), and myelodysplastic syndromes (MDS) stem cells." (PMID 29534016, 2018). "CD99 was demonstrated to be a potential target for antibody therapy on T-acute lymphoblastic leukemia (T-ALL)." (PMID 38804310, 2024). "Among B cells, B cell precursors with acute lymphoblastic leukemia (BCPs-ALL) express mainly the long form of CD99, while in normal B cell precursors (BCPs), CD99 is downregulated during differentiation." (PMID 29534016, 2018). "CD99, a type I transmembrane protein, emerges as a promising therapeutic target due to its heightened expression in T cell acute lymphoblastic leukemia (T-ALL)." (PMID 39595598, 2024). "CD99 has been found to be upregulated in acute lymphoblastic leukemias (ALL)." (PMID 27655702, 2016). "Additional markers, such as for B-cell precursor phenotype (TdT, CD34, and CD99) can help rule out an acute lymphoblastic leukemia." (PMID 29850589, 2018).
acute myeloid leukemia (12 papers, 2018 to 2025). Acute myeloid leukemia (AML) is a group of neoplasms arising from precursor cells committed to the myeloid cell-line differentiation. "Cluster of differentiation 99 (CD99) is a receptor that is significantly upregulated in acute myeloid leukemia (AML)." (PMID 39007347, 2024). "This study investigates a dual-targeting strategy in acute myeloid leukemia (AML), focusing on FLT3 and CD99." (PMID 39007347, 2024). "Previous studies indicate that CD99 is a marker of stem cells in acute myeloid leukemia (AML) and myelodysplastic syndrome, and is also a marker for prospective separation of leukemic stem cells (LSCs) from functionally normal hematopoietic stem cells in AML." (PMID 34872612, 2021). "Similarly, CD99 regulates FLT3-ITD localization, suggesting its potential in immunotherapy for acute myeloid leukemia." (PMID 40427525, 2025). "CD99 exhibits an oncogenic function, which showed strong expression levels on various cancer cell types, including T cell lineage leukemia/lymphoma, Ewing sarcoma (EWS), breast cancer, acute myeloid leukemia (AML), and myelodysplastic syndromes (MDS)." (PMID 38468825, 2024).
glioblastoma (12 papers, 2013 to 2025). The most malignant astrocytic tumor (WHO grade IV). "In this single-center retrospective analysis, we assessed the expression of CD99, both by IHC and by qRT-PCR, in glioblastoma tumor samples and evaluated its association with OS." (PMID 38607036, 2024). "In another study, a high CD99 expression was associated with response to antiangiogenic therapy in patients with recurrent glioblastoma." (PMID 38607036, 2024). "Finally, we performed immunohistochemistry and immunofluorescence staining on glioblastoma samples from the high‐ and low‐risk score groups, confirming the higher expression of CD99, EGFR and VEGFA in the high‐risk group." (PMID 38687049, 2024). "Despite not finding a direct association with prognosis, the fact that CD99 is detectable in most glioblastoma cases, along with the preclinical evidence supporting its role in glioblastoma pathogenesis and progression, suggests that it could still serve as a potential therapeutic target." (PMID 38607036, 2024). "Preclinical and translational studies have confirmed the overexpression of CD99 in glioblastoma and highlighted its role in promoting glioblastoma cell migration and invasion." (PMID 38607036, 2024). "This represents a prerequisite for the potential utility of CD99 as a therapeutic target in those glioblastomas that overexpress this molecule." (PMID 38607036, 2024). "Various preclinical studies have investigated the role of CD99 in glioblastoma pathogenesis and progression." (PMID 38607036, 2024). "In conclusion, our study provides further evidence on the expression and potential significance of CD99 in glioblastoma." (PMID 38607036, 2024). "Further investigations are needed to better understand the function of CD99 in different glioblastoma subtypes, its interactions with other relevant biomarkers, and its involvement in the response to various treatments." (PMID 38607036, 2024). "Overall, these studies highlight a crucial role of CD99 in glioblastoma, particularly in promoting the migration and invasiveness of cancer cells, though an effect on regulated cell deaths was also reported." (PMID 38607036, 2024). "In summary, our research shows overexpression of CD99 in 22% of glioblastoma samples and lower expression in further 61% of the cases." (PMID 38607036, 2024). "It confirms that the full-length, wild-type isoform of CD99 is exclusively expressed in glioblastoma." (PMID 38607036, 2024). "In glioblastoma, high CD99 expression has been found to promote tumour cell migration, invasion and the formation of an immune‐suppressive microenvironment." (PMID 38687049, 2024). "The purpose of this retrospective study is to investigate the expression levels and prognostic impact of CD99 in a single-center cohort of patients with glioblastoma, supporting its relevance as a promising therapeutic target." (PMID 38607036, 2024). "CD99 in tumor blood vessels inhibits tumor formation; however, CD99 expression is increased in glioblastoma patients, and when divided according to molecular type, CD99 expression is higher in the mesenchymal type than in the pro-neural type." (PMID 36732815, 2023). "Branched multipeptides from ERBB2, BIRC5, and CD99 stably bound with T2 cells, and multipeptide-pulsed denditric cells–cytotoxic T lymphocytes exhibited remarkable cytotoxic activity against primary glioblastoma cells." (PMID 29534016, 2018). "IPA connections of Grade IV Glioblastoma Markov genes reveled direct interactions between CD99 and ANXA2, and EGFR and RAB31 genes." (PMID 23737970, 2013). "CD99 is expressed at higher levels in glioblastoma compared to normal brain or lower-grade gliomas." (PMID 38607036, 2024). "In a study of cDNA microarrays, CD99 emerged as one of the genes differentially expressed between glioblastoma and normal encephalic tissue and was part of a selection of 31 genes encoding membrane proteins that represent potential targets for cellular or antibody-based immunological therapies." (PMID 38607036, 2024).
glioblastoma (continued). "CD99 might therefore be a relevant therapeutic target, particularly in counteracting the typical tendency of glioblastoma cells to disseminate widely throughout the brain tissue." (PMID 38607036, 2024). "Another study exploring genes highly expressed in placenta and potentially related to an invasive phenotype found that CD99 exhibited the highest relative mRNA expression in glioblastoma compared to normal brain tissue and its expression was associated with larger, multilobar tumor extension." (PMID 38607036, 2024). "An analysis of the glioblastoma TCGA casuistry, although not directly comparable with our casuistry, confirms a lack of association of CD99 mRNA levels with OS and PFS." (PMID 38607036, 2024). "Given its frequent expression in glioblastoma, CD99 might be a potential target for pure anti-CD99 antibodies or, in the new era of ADCs with novel anti-CD99, combined with temozolomide." (PMID 38607036, 2024). "EREG is the core onco-immunological biomarker of CuAS and modulates the cross-talk between VEGF and CD99 signaling in glioblastoma, and CuAS may provide support for immunotherapy and chemotherapy." (PMID 36647156, 2023). "In addition, peptides from CD99 have been described as promising candidates for immunotherapeutic glioblastoma treatment." (PMID 29534016, 2018). "Regarding tumors of the central nervous system, a comprehensive study across a large series of astrocytomas of various grades has indicated a clear relationship between tumor aggressiveness and CD99 expression, with glioblastomas showing the highest positivity." (PMID 29305692, 2018). "The expression of CD99 in glioblastoma (GBM) has been the focus of extensive research, with several studies investigating its role in various aspects of the disease." (PMID 40427525, 2025). "However, the expression of CD99 varies in the various subtypes of glioblastoma and in different glioblastoma cell lines, and its biological impact, which has been studied mainly on individual cell lines, could also be variable, as occurs among different types of neoplasms." (PMID 38607036, 2024). "Taken together, CuAS can evaluate glioblastoma aggressiveness, modulate the cross-talk between VEGF/CD99 signaling, and provide support for immunotherapy and chemotherapy." (PMID 36647156, 2023). "This opens interesting therapeutic perspectives for tumors in which CD99 acts as on oncogene, such as EWS, ALL, MDS, AML and glioblastoma." (PMID 29305692, 2018). "In the present study, we investigated the possibility of using peptide immunotherapy for glioblastoma by using ERBB2-, BIRC5- and CD99-specific CTLs generated by multipeptide-pulsed DCs." (PMID 27409668, 2016). "In summary, we have described a branched multipeptide vaccine capable of stimulating a response to multiple CD8+ T cell epitopes from glioblastoma-TAAs such as ERBB2, BIRC5 and CD99." (PMID 27409668, 2016). "In the present study, we designed a peptide immunotherapy for glioblastoma using ERBB2, BIRC5 and CD99 peptides as TAAs." (PMID 27409668, 2016). "This study confirms a high expression of CD99 in glioblastoma but does not show any significant impact on survival." (PMID 38607036, 2024). "Therefore, mAbs against CD99 have promising preclinical effectiveness in several types of tumors (EWS, AML, ALL and glioblastoma) and are selective for malignant stem cells." (PMID 29305692, 2018). "In our previous study, we detected positive expression of v-erb-b2 erythroblastic leukemia viral oncogene homolog-2 (ERBB2), baculoviral IAP repeat containing-5 (BIRC5) and the glycoprotein CD99 in most glioblastoma tissues, and negative expression in normal brain tissues." (PMID 27409668, 2016).